SAA1 (serum amyloid A1)
Diseases named in the same sentence as SAA1 in open-access papers (continued):
Sharing a sentence is not in itself a finding about the gene and the disease.
E. coli infection (1 paper, 2024). "In accordance with mouse lethality, E. coli infection-induced pyroptosis of macrophages was significantly elevated by the addition of SAA1, indicating that SAA1 augments the intensity of noncanonical inflammasome response." (PMID 38297162, 2024). "In support of these results, we found that exogenous SAA1 potentiated the secretion of caspase-11 and GSDMD cleavage from BMDMs upon E. coli infection." (PMID 38297162, 2024). "To further confirm whether the blockade of Rev-erbα by SR8278 could regulate noncanonical inflammasome-mediated SAA1 production and pyroptosis in macrophages, we examined the potential effect of SR8278 treatment in BMDMs upon E. coli infection." (PMID 38297162, 2024).
enteritis (1 paper, 2022). Inflammation of the small intestine. "This study primarily focuses on the role of SAA1 in enteritis, and the expression levels of the subtypes SAA2-4 were also examined." (PMID 35303008, 2022). "Using the DSS enterocolitis mouse model, the expression of SAA1-4 and CRP was evaluated in the liver and several parts of the intestinal tract to determine the main organ of SAA expression in enteritis." (PMID 35303008, 2022).
Fabry disease (1 paper, 2022). Fabry disease (FD) is a progressive, inherited, multisystemic lysosomal storage disease characterized by specific neurological, cutaneous, renal, cardiovascular, cochleo-vestibular and cerebrovascular manifestations. "In the case of SAA1, such a correlation emerges from a case study according to which the mRNAs of proinflammatory genes, such as SAA1, were up-regulated in the testicular tubule microenvironment of an infertile man presenting with Fabry’s disease." (PMID 36613967, 2022).
Fever (1 paper, 2024). Body temperature elevated above the normal range. "Furthermore, we found that fever‐cause categories showed the strongest correlation with PIGR (R = 0.47), SAA1 (R = 0.46), and SAA2 (R = 0.42), although no distinct pattern was discernible for fever‐cause." (PMID 39441646, 2024). "Furthermore, the FN‐category correlated with inflammation‐related proteins such as CRP (R = 0.44), SAA1 (R = 0.44), and SAA2 (R = 0.40), and their levels were indeed increased in samples obtained from patients with mild‐FN and complicated‐FN compared to non‐fever patient samples." (PMID 39441646, 2024).
fibrosis (1 paper, 2021). the formation of excess fibrous connective tissue in an organ or tissue in a reparative or reactive process. "Finally, excessive recruitment and deposition of HSCs at injury sites is a key driver of liver cirrhosis suggesting that SAA1/TLR2 axis may provide a novel target to anti-fibrosis drug development." (PMID 34113824, 2021).
Fulminant hepatic failure (1 paper, 2020). Hepatic failure refers to the inability of the liver to perform its normal synthetic and metabolic functions, which can result in coagulopathy and alteration in the mental status of a previously healthy individual. "Finally, the five genes (TDO2, HP, SERPINA3, LBP and SAA1) validated in hBMSC transplantation with a fulminant hepatic failure (FHF) model in pigs could be potential biomarkers for the characterization of hBMSC-HLCs." (PMID 32038110, 2020). "In vivo transdifferentiation of hBMSCs in pigs with fulminant hepatic failure confirmed the similarly upregulated expression of 5 hepatogenic genes (TDO2, HP, SERPINA3, LBP and SAA1), showing a 150-fold change in liver tissues at 7 days after hBMSC transplantation." (PMID 32038110, 2020).
glaucoma (1 paper, 2025). Increased pressure in the eyeball due to obstruction of the outflow of aqueous humor. "Increased expression of SAA1/2 has been observed in the trabecular meshwork tissue and cells of glaucoma patients, and it has been shown that this increase contributes to the glaucoma phenotype characterized by elevated intraocular pressure." (PMID 40003925, 2025).
gram-negative bacterial infections (1 paper, 2022). Infections caused by bacteria that show up as pink (negative) when treated by the gram-staining method. "Inducible expression of SAA1 in the acute phase may protect the host from Gram-negative bacterial infection by reducing LPS-induced tissue damage." (PMID 35573776, 2022).
HCMV infection (1 paper, 2017). "However the co-occurrence (ratio between SAA1 and APOE) of the two proteins was with best performance (AUC = 86.7%, specificity = 78.3%, sensitivity = 93.3%) identifying HCMV infections." (PMID 29042594, 2017).
hyperlipidemia (1 paper, 2019).
ichthyosis (1 paper, 2016). Disorders of cornification that are characterized by visible scaling and/or hyperkeratosis of most or all of the skin. "Interestingly, we observed a significant increase in the transcripts for S100A8, S100A9, Krt1, and Saa1, which have been shown to maintain skin integrity, barrier function, inflammation, and ichthyosis in human skin." (PMID 27556734, 2016).
idiopathic pulmonary arterial hypertension (1 paper, 2025). A sporadic form of pulmonary arterial hypertension (PAH) characterized by elevated pulmonary arterial resistance leading to right heart failure. "SAA1 was shown to be related to the pathogenesis of idiopathic pulmonary arterial hypertension, regardless of sex differences." (PMID 40357364, 2025).
inflammatory skin disease (1 paper, 2019). Inflammatory skin disorders covers a broad category that includes many conditions ranging in severity, from mild itching to grave medical health complications These disorders are common in people of all ages and races. "SAA1 and SAA2 (another member of SAA family) contribute to inflammatory skin diseases such as acne." (PMID 31281837, 2019).
interstitial lung disease (1 paper, 2024). A diverse group of lung diseases that affect the lung parenchyma. "Of note, SAA1 and S100A8 were associated with interstitial lung disease in patients with DM in a previous study." (PMID 38396646, 2024).
intervertebral disc degeneration (1 paper, 2020). "Moreover, Saa1 is the direct target of miR-660, which can protect nucleus pulposus cells from TNFa-induced apoptosis in intervertebral disc degeneration." (PMID 32969837, 2020).
iridocyclitis (1 paper, 2023). "Higher SAA1 serum levels were demonstrated in JIA patients vs healthy CTR correlating with the number of active joints, iridocyclitis development, and high CRP and ESR expression, suggesting its potential as a disease activity marker." (PMID 37205098, 2023).
kidney cancer (1 paper, 2021). Primary or metastatic malignant neoplasm involving the kidney. "Collectively, we found that SAA1 expression was up-regulated in kidney cancer tissues and its high expression was predictive of advanced tumor stage." (PMID 34084746, 2021).
leishmaniasis (1 paper, 2025). Infectious disease that is transmitted through the bite of hematophagous female phlebotomine sand flies. "Although the potential of SAA1/2 and ITGB1 as biomarkers has been described in other systemic diseases, this study highlights their significance specifically in the context of leishmaniasis." (PMID 41019078, 2025).
leukemia (1 paper, 2025). A malignant (clonal) hematologic disorder, involving hematopoietic stem cells and characterized by the presence of primitive or atypical myeloid or lymphoid cells in the bone marrow and the blood. "In AML, the SAA1 protein is secreted by osteoblasts and is capable of inducing a pro-proliferative effect on AML blasts and leads to the self-reinforced progression of leukemia." (PMID 40299483, 2025).
muscular atrophy (1 paper, 2014). The loss of muscle tissue due to inactivity or disease. "A role for both SAA1 and IL-6 in muscular atrophy was recently reported." (PMID 24651840, 2014).
myositis (1 paper, 2025). "The hPBMC mice exhibit elevated serum levels of creatine kinase and aspartate transaminase, markers of myositis, and increased expression levels of myositis-related genes, such as vascular cell adhesion molecule 1, intercellular adhesion molecule 1, and serum amyloid A1, in muscle tissues." (PMID 39810259, 2025).
otitis media (1 paper, 2019). Inflammation of the anatomical structures of the middle ear, which is most often caused by an infectious process. "Two differentially expressed genes CR1 and SAA1 overlap in middle ear, sinus, and lower airway samples and are potentially novel genes for otitis media susceptibility." (PMID 32010199, 2019).
ovarian tumor (1 paper, 2020). "Firstly, we examined the expression of SAA-1, SAA-2, and SAA-4 in ovarian tumor tissues and OVCAR-3 cells." (PMID 32517794, 2020). "We found that SAA-1 and SAA-4 could be expressed in ovarian tumor tissues and OVCAR-3 cell, but SAA-2 could not." (PMID 32517794, 2020).
pancreatic ductal adenocarcinoma (1 paper, 2021). An infiltrating adenocarcinoma that arises from the epithelial cells of the pancreas. "The additional cluster 6, which is specific to the cornea sample with limbal dysplasia, displayed high expression of SAA1, a marker of pancreatic ductal adenocarcinoma tumor stroma primarily composed of cancer-associated fibroblasts." (PMID 33865984, 2021).
papillary renal cell carcinoma (1 paper, 2023). A rare subtype of renal cell carcinoma, arising from the renal tubular epithelium and showing a papillary growth pattern, which typically manifests with hematuria, flank pain, palpable abdominal mass or nonspecific symptoms, such as fatigue, weight loss or fever. "BDKRB1, NMUR2, PMCH, and SAA1 may contribute to the occurrence and development of papillary renal cell carcinoma." (PMID 36785669, 2023).
Parkinson disease (1 paper, 2013). A progressive degenerative disorder of the central nervous system characterized by loss of dopamine producing neurons in the substantia nigra and the presence of Lewy bodies in the substantia nigra and locus coeruleus. "We were specifically drawn to a group of genes that were significantly dysregulated in blood and brain, including Necab3, Apbb2, App, Psen1, Saa1, Prkcg, Park2, Snca and Prnp, because of their involvement in neurodegenerative diseases, such as Alzheimer’s and Parkinson’s disease." (PMID 24278249, 2013).
periodontal diseases (1 paper, 2022). "CRCR4, CXCL1, and SAA1 regulate immune cell distribution and induce inflammatory cell recruitment in periodontal diseases." (PMID 36457739, 2022).
polycystic kidney disease (1 paper, 2015). A usually autosomal dominant and less frequently autosomal recessive genetic disorder characterized by the presence of numerous cysts in the kidneys leading to end-stage renal failure. "Cytotherapy with renal cells expressing wild type Pkhd1 and tubulogenic serum amyloid A1 had powerful and sustained beneficial effects on renal function and structure in the polycystic kidney disease model." (PMID 26136112, 2015).
rectal cancer (1 paper, 2021). A primary or metastatic malignant neoplasm that affects the rectum. "Besides CXCL1, CXCL2, and CXCL3, we mined seven other hub genes related to rectal cancer, including SAA1, AGT, GNG4, SST, SSTR2, GAL, and CXCL12." (PMID 34269159, 2021). "Seven hub genes, including SAA1, AGT, GNG4, GAL, CXCL1, CXCL2, and CXCL3, were upregulated in rectal cancer tissues." (PMID 34269159, 2021).
Renal amyloidosis (1 paper, 2019). A form of amyloidosis that affects the kidney. "Moreover, modifier genes encoding components of amyloid A deposits, such as serum amyloid A1 (SAA1), have been significantly and independently associated with renal amyloidosis." (PMID 32082075, 2019).
respiratory infection (1 paper, 2025). "This study investigates the role of SAA1 in the early stages of respiratory infection by S. pneumoniae and its potential contribution to bacterial adaptation under acidic stress." (PMID 40572197, 2025).
Salmonella Infections (1 paper, 2021). Infections with bacteria of the genus SALMONELLA. "Some of them, such as tyrosine-protein phosphatase non-receptor type 1 (PTPN1), serum amyloid A-1 protein (SAA1) and chloride intracellular channel protein 1 (CLIC1), although previously reported in Salmonella infections, we have for the first time clearly associated them with SPI-2 effectors." (PMID 34461813, 2021).
sarcopenia (1 paper, 2024). Progressive decline in muscle mass due to aging which results in decreased functional capacity of muscles. "Importantly, we determined that increased SAA1 might be involved as a factor in developing sarcopenia in NAFLD." (PMID 38533529, 2024). "Increased SAA1 might be involved as a regulatory factor in developing sarcopenia in NAFLD." (PMID 38533529, 2024).
selenium deficiency (1 paper, 2024). A nutritional deficiency disease resulting from inadequate selenium levels in the body, which can lead to impaired function of selenoproteins essential for antioxidant defense and thyroid hormone metabolism. "Our analysis identified multiple DEGs that may be associated with cartilage development and selenium deficiency, such as PTH1R and SAA1." (PMID 38673933, 2024).
skin infection (1 paper, 2025). An inflammatory process affecting the skin, caused by bacteria, viruses, parasites, or fungi. "In a study of skin infection by S. aureus, recombinant human SAA1 and SAA2 and mouse Saa1, Saa2 and Saa3 all bind bacterial membrane and exhibit a stronger bactericidal effect in lower pH conditions." (PMID 39940756, 2025).
Ss (1 paper, 2020). "To determine the effect of Ss infection on systemic inflammation in T2DM, we measured the levels of acute phase proteins (α-2M, CRP, haptoglobin and SAA-1) in Ss+ and Ss− individuals." (PMID 32984066, 2020).
uremia (1 paper, 2020). A clinical syndrome associated with the retention of renal waste products or uremic toxins in the blood. "Only SAA1, albumin, phospholipase A2 and apoC-III were differentially expressed between HDL from controls and those with uremia." (PMID 32921312, 2020).
uveitis (1 paper, 2021). An inflammatory process affecting a part of or the entire uvea. "In a pilot study on three children with JIA-uveitis, elevated levels of proteins associated with inflammatory arthritis (SEMA3G, TIMP1, HEXB, ERN1, and SAA1) was found, in addition to elevated levels of sCD14, S100A8, and SAA1, but reduced levels of S100A9, LAP3, TTR, and MIF." (PMID 34438537, 2021).
viral pneumonia (1 paper, 2022). Inflammation of the lung parenchyma that is caused by a viral infection. "In previous work, we have also discovered increased serum level of IL-10, IL-6, as well as acute-phase proteins (CRP and Serum amyloid A1) in the same patients with SARS-CoV-2 induced viral pneumonia." (PMID 36298646, 2022).
Wilms tumor (1 paper, 2014). An embryonal neoplasm characterized by the presence of epithelial, mesenchymal, and blastema components. "SAA1 is highly expressed during inflammation and has been identified as a potential Wilms’ tumor marker, as one of a two-protein signature model for prognosis prediction in metastatic RCC, and as a predictor in fatal outcome in RCC." (PMID 25472429, 2014).
tumor (104 papers, 2011 to 2026). "Our exploration of intercellular communications involving PLOD2 + SAA1 + tumor cells provides insights into the underlying molecular mechanisms driving tumor development and metastasis." (PMID 38951896, 2024). "Collectively, these results suggest that LCN2 deletion induces SAA1 hypoactivation, which is assumed to lead to tumor angiogenesis in GC based on the role of SAA1 polymorphisms." (PMID 35705840, 2022). "To determine the diagnostic value of SAA1, we performed ROC curve analysis between tumor tissues with different stage or grade and normal tissues." (PMID 34084746, 2021). "The SAA protein, encoded by SAA1, is highly induced during the acute-phase response and plays an important role in lipid metabolism, bacterial clearance, and tumor pathogenesis." (PMID 33478117, 2021). "A proteomic analysis of serum and tissue samples from RCC patients revealed that SAA1 levels were associated with tumor stage and metastasis, which indicates that SAA1 acts as a potential specific biomarker for aggressive clear cell RCC." (PMID 32921632, 2020). "A transcriptomic analysis of patients with cervical squamous cell carcinoma revealed that SAA1 levels were associated with tumor size, lymphatic metastasis, and cancer cell invasion." (PMID 29603594, 2018). "Of the other genes that are significantly upregulated with advanced disease, SAA1 (serum amyloid A1) is part of the family of highly homologous acute-phase proteins that have been associated with tumor progression and reduced survival in a range of cancers." (PMID 26893359, 2016). "Tumor-induced inflammation causing secretion of serum amyloid A1 (SAA-1) induced differentiation of suppressive IL-10-producing neutrophils." (PMID 25389427, 2014). "Our research indicates that PLOD2 + SAA1 + tumor cells might be capable of communicating with tumor-associated macrophages (TAMs) through specific ligand-receptor pairs, such as MIF-(CD74 + CXCR4), MDK-LRP1 and C3-C3AR1." (PMID 38951896, 2024). "Finally, immunohistochemistry results of 66 paraffin-embedded specimens indicated that SAA1 was strongly expressed in the tumor samples and was associated with tumor metastasis, stage, and grade." (PMID 38862642, 2024). "Therefore, further investigation should be conducted to clarify the accuracy of a combined analysis of SAA1 expression, the amounts of tumor-infiltrating mast cells resting, and the types of mutation driven prior to SAA1 inhibitor treatment for ccRCC patients." (PMID 37108666, 2023). "SAA1, a major acute-phase protein, is highly expressed in response to inflammation and tissue injury, and SAA1’s high expression is significantly linked to poor differentiation of tumor cells." (PMID 36091778, 2022). "SAA1 is highly expressed in response to tissue injury and inflammation, and its highly expression is associated with chronic inflammation, lipid metabolism and tumor pathogenesis." (PMID 29740512, 2018). "Tumour-derived SAA1 reprograms TAM through FPR2-mediated JAK2-STAT3 signalling to induce an immunosuppressive phenotype." (PMID 42145073, 2026). "Consistently, supplementing primary HER2-positive tumor cultures with recombinant SAA1, SAA2, or THBS4 peptides enhanced tumor cell proliferation and migration." (PMID 41387465, 2025). "One example is that acute-phase Saa1 and Saa2 production in mouse liver serves to abrogate tumor surveillance by T cells, thus promoting tumorigenesis." (PMID 39940756, 2025). "Immunohistochemical analysis of tumor tissues revealed a marked reduction in SAA1 expression in the knockdown group, along with decreased Ki67 and N-Cadherin levels and increased E-Cadherin expression." (PMID 41029721, 2025). "SAA1 is one of the major proteins of amyloid A, which plays an important role in lipid metabolism, bacterial infection, arterial inflammation, and tumor." (PMID 40421421, 2025).